FLOT1 (flotillin 1)
Diseases named in the same sentence as FLOT1 in open-access papers (continued):
Sharing a sentence is not in itself a finding about the gene and the disease.
tumor (continued). "FLOT1 had higher expression in C4 subtype, and it predicted the dismal survival, which suggested the tumor promoting effect." (PMID 36300104, 2022). "Flotillin 1 is a membrane receptor protein that is considered to promote metastasis and tumor invasion by influencing the Erk1/2, p38, JNK and NF-κB/p65 signaling pathways." (PMID 34295245, 2021). "Mechanically, miR-124-3p has a key role in repressing tumor progression by targeting Cav-1 and Flotillin 1 (FLOT1)." (PMID 31759347, 2019). "Knocking down flotillin-1 or flotillin-2 in HCCLM3 cells by shRNA significantly lowered insufficient RFA-induced tumor growth, EMT changes, and metastasis in vitro and in vivo." (PMID 30820716, 2019). "Our meta-analysis also suggested that flotillin-1 expression level was related to histological grade and depth of primary tumor invasion." (PMID 28881760, 2017). "Zebrafish embryos were injected with fluorescent-labeled tumor cells overexpressing Flotillin-1 to analyze tumor metastasis." (PMID 28718799, 2017). "Zebrafish embryos have also been used to evaluate the effect of Flotillin-1 overexpression in KB cells (a subline of the KERATIN-forming tumor cell line HeLa), which are an OSCC cell line." (PMID 28718799, 2017). "Recently, several studies found that Flotillin-1 was closely related to the occurrence and development of tumor." (PMID 28881760, 2017). "In numerous studies, Flotillin-1 was reported to be involved in tumor progression, indicating prognosis in various types of cancer." (PMID 28881760, 2017). "Our results indicated an important role for Flotillin-1 in the development and progression of tumor, the precise mechanisms of its effects have been demonstrated, however, it should be proved with further well-designed clinical studies." (PMID 28881760, 2017). "According to the review of relevant publications, Flotillin-1 has participated and regulated the tumor development processes with multiple pathways." (PMID 28881760, 2017). "To further explore the function and role of FLOT1 and histone H1 in S100A11-mediated tumor progression, we performed gain- and loss-of-function assays." (PMID 27181092, 2016). "Quantitative evaluation performed after normalization confirmed the results; overexpression of caveolin-1 and flotillin-1 was recorded in most tumor samples compared to control ones." (PMID 25243186, 2014). "In this study, we demonstrated that FLOT1 was overexpressed in RCC versus adjacent non-tumor tissues and that silencing FLOT1 significantly inhibited the proliferation and tumorigenesis of RCC cells through regulation of the AKT/FOXO3a pathway." (PMID 24886554, 2014). "Analyzing of 196 primary HCC samples indicated that FLOT1 expression was strongly correlated with tumor size (P = 0.025), clinical stage (P<0.002), CLIP stage (P<0.001), vascular invasion (P<0.001), relapse (P<0.001), and serum AFP levels (P = 0.025)." (PMID 23840303, 2013). "The ectopic expression of miR-124 inhibits cell proliferation and migration by downregulating FLOT1, which indicates the internal mechanism of tumor suppression of miR-124." (PMID 24330780, 2013). "Univariate Cox regression analyses revealed that higher level of FLOT1, Tumor size, Tumor multiplicity, clinical Stage, CLIP stage, vascular invasion, relapse as well as serum AFP levels were all were worse predictors for HCC patients." (PMID 23840303, 2013). "In the 196 cases of tested HCC samples, FLOT1 protein level was positively correlated with Tumor size (P = 0.025), clinical stage (P<0.002), CLIP stage (P<0.001), vascular invasion (P<0.001), relapse (P<0.001), and serum AFP levels (P = 0.025)." (PMID 23840303, 2013). "However, the FLOT1 HR subgroup exhibited significantly lower 5-year OS rates than the FLOT1 LR subgroup among patients with advanced tumor stages (38.6% vs. 51.6% at 5 years, P = 0.00944)." (PMID 40335491, 2025).
tumor (continued). "This may account for the diminished protein levels of FLOT-1 in EVs isolated from the serum of 4T1 tumor-bearing mice receiving reserpine." (PMID 38405101, 2024). "Interestingly, TEVs isolated from the serum of 4T1-GFP tumor-bearing mice on reserpine chow carried less FLOT-1, and ALIX and GAPDH with post-translational modifications." (PMID 38405101, 2024). "Moreover, FLOT1 mRNA expression was significantly higher in tumor tissues compared to adjacent non-tumor tissues." (PMID 39193618, 2024). "Interestingly, analysis of EVs from 4T1 tumor-bearing mice demonstrated that the reserpine treatment resulted in EVs with less flotillin-1 (FLOT-1) and GAPDH bands of larger or smaller size compared to the other treatment conditions." (PMID 38405101, 2024). "Indeed, FLOT1 expression correlated with infiltration of immune cells in NSCLC tumor tissue samples." (PMID 37131290, 2023). "Considering that FLOT1 is the upstream signaling molecule of STING and PD-L1 signaling pathway, we further explored whether FLOT1 was involved in the immune regulation of tumor microenvironment." (PMID 37131290, 2023). "Flotillin‐1(FLOT1) has long been recognized as a tumour‐promoting gene in several types of cancer." (PMID 36647700, 2023). "In summary, this study is the first, to the best of our knowledge, to unveil that NSCLC cells can elevate FLOT1 expression to launch a defense against radiotherapy through stimulating cell migration, impeding radiation-induced DNA damage, and inducing tumor immune desertification." (PMID 37131290, 2023). "Interestingly, the expression of PD-L1 was higher in tumor tissues with FLOT1 high relative expression than low relative expression." (PMID 37131290, 2023). "Both EVs from tumour tissues contain EV proteins, including Flotillin-1 as well as Calnexin." (PMID 31497264, 2019). "In our study, we also found the overexpression of FLOT1 in BCa tissues in contrast with paired adjacent non-tumor tissues, and the down-regulation of FLOT1 could sharply inhibit the proliferation of BCa cells via activating AKT/FOXO3a signaling pathway." (PMID 28549468, 2017). "However, the biological role and molecular mechanism of FLOT1 during tumor metastasis remain to be clarified." (PMID 26646322, 2016). "Moreover, the volume of the lymph nodes, numbers of pan-cytokeratin-positive tumor cells and ratio of metastatic to total inguinal lymph nodes dissected were significantly reduced by knocking down of FLOT1." (PMID 26646322, 2016). "A high level of expression of Flot-1 or Flot-2 can enhance tumor growth and tumor cell migration." (PMID 26206082, 2015). "In addition, 50.5% (43/85) of the matched cases showed higher flotillin 1 expression in the tumor compared to normal tissues while only 13% of the matched cases showed the reverse trend." (PMID 25948494, 2015). "In addition, the expression of caveolin-1 and flotillin-1 staining was significantly increased along with the progression of tumor grades I to III." (PMID 25243186, 2014). "Immunohistochemistry staining indicated that the high expression level of FLOT1 protein in histological sections is strongly correlated with aggressive characteristics of human HCC (tumor size, advanced stages, vascular invasion and relapse) and reduced survival time of patients with HCC." (PMID 23840303, 2013). "Treatment with 3‐DAA might reduce the m6A level of FLOT1 mRNA, affecting tumor formation." (PMID 40066501, 2025). "Based on these findings, FLOT1 may play a potential role in the tumour microenvironment." (PMID 36647700, 2023). "Therefore, Flotillin-1 plays an important role in the occurrence and development of tumor and may serve as a new prognostic marker for cancer." (PMID 28881760, 2017). "Patients with high FLOT1 better simulation of tumor invasion survival (P = 0.003; hazard ratio (HR) (95% confidence interval (CI)) = 2.63 (1.40–4.93)) and disease-free survival (P = 0.003; HR (95% CI) = 2.18 (1.29–3.67)) compared to patients with low FLOT1 expression." (PMID 26646322, 2016).
tumor (continued). "Moreover, a three-dimensional spheroid invasion assay, which is considered to be a better simulation of tumor invasion in vivo, revealed that FLOT1-overexpressing cells exhibited active invasive behaviors, characterized by the formation of outward projections from individual cells." (PMID 26646322, 2016). "We found that the function of FLOT1 was mainly related to epithelial‐mesenchymal transition (EMT), inflammatory response, tumor inflammation, proliferation, extracellular matrix (ECM) related genes, and cellular response to hypoxia." (PMID 40066501, 2025). "Concurrently, miR‐124‐3p can exert tumor‐suppressive effects by targeting CAV1 and FLOT1, thus inhibiting the PI3K/AKT and Ras/MAPK signaling pathways." (PMID 39092291, 2024). "Therefore, FLOT1 may be a potential target for brain‐related disease including tumour." (PMID 36647700, 2023). "In this study, we demonstrated that the expression of FLOT1 is inversely correlated with response to radiotherapy in NSCLC cell lines, subcutaneous mouse xenograft tumor model, and patients." (PMID 37131290, 2023). "In tumor tissues from NSCLC patients, FLOT1 was dramatically upregulated compared to their matched adjacent normal lung tissues." (PMID 37131290, 2023). "With respect to PBMC, most tumor cells had superior amounts of GM1 and flotillin-1, detected by means of the affinity to cholera toxin B and a specific monoclonal antibody, respectively." (PMID 31767857, 2019). "In accordance with studies in other cancers, knocking down FLOT1 and/or FLOT2 inhibited the invasion, migration, and anchorage-independent growth of HCCLM3 cells in vitro and decreased their tumor growth and metastasis in vivo." (PMID 30820716, 2019). "In this study, we investigated FLOT1 and FLOT2 expression in insufficient RFA tumor tissues in vivo and in heat-treated HCC cells in vitro, and further explored the roles of flotillins in altering the metastatic potential of residual HCC cells." (PMID 30820716, 2019). "Interestingly, FLOT1 has been reported to be crucial for coordinated assembly of signaling complexes and signal transduction induced by TNF-α, EGF, HGF and IGF-l, suggesting that FLOT1 might play an important role in mediating the heterotypic signals originate in the tumor microenvironment." (PMID 26646322, 2016). "Thus, such a FLOT1-mediated mechanism may enhance the heterotypic signals induced by extrinsic stimuli to induce the acquisition of mesenchymal traits by cancer cells and promote metastasis during the late stages of tumor progression." (PMID 26646322, 2016). "Herein, we report that flotillin-1 (FLOT1), a component of lipid raft, which was reported to be involved in tumor progression, was robustly upregulated in the NPC samples with lymph node metastasis." (PMID 26646322, 2016). "We finally demonstrated that FLOT1 might enhance radioresistance through facilitating EMT process, suppressing radiation-induced DNA damage, and reprogramming the tumor immune microenvironment via STING signaling pathways in NSCLC." (PMID 37131290, 2023). "Moreover, FLOT1 depletion enhanced radiation-induced DNA damage, thereby increasing the radiation lethality for NSCLC cells and promoting radiation-mediated tumor regression in animal models and patients with NSCLC." (PMID 37131290, 2023). "Two-samples t test revealed that the expression of flotillin 1 in cancer/tumor samples is significantly higher than that of noncancer/normal tissues (p < 0.01)." (PMID 25948494, 2015). "In addition, multivariate Cox regression analysis revealed that tumor multiplicity, clinical stage, CLIP stage, vascular invasion and FLOT1 expression were independent prognostic markers for HCC." (PMID 23840303, 2013). "By real-time RT-PCR analysis, the tumor/adjacent non-cancerous (T/N) ratio of FLOT1 mRNA expression was >2-fold in all these samples, and the highest ratio was up to about 40-fold." (PMID 23840303, 2013).
tumor (continued). "However, proteins such as flotillin 1 involved in clathrin-mediated endocytosis have not been reported to differentially expressed in GC tumours in previous researches." (PMID 25948494, 2015). "Furthermore, six tumor progression genes (GNAI2, ODC1, APP, TNFRSF12A, BASP1, and LARP6) and nine migration and metastasis‐related genes (MSN, FLOT1, LAMB3, MYL9, ITGB1, FTH1, TPM4, and PMEPA1), which could explain the invasive characteristics of SCC, were identified." (PMID 40776410, 2025). "Furthermore, FLOT1 depletion-boosted DNA damage activated STING signaling pathway and promoted the production of CCL5 and CXCL10 that can drive CD8+ T lymphocytes chemotaxis, thereby reprogramming tumor immune microenvironment and triggering the antitumor immune response." (PMID 37131290, 2023). "However, the function and expression of FLOT1 in GBM progression and the tumour microenvironment have not been investigated." (PMID 36647700, 2023). "Here, we found that the depletion of FLOT1 boosted radiation-induced DNA damage, hence it is worth exploring whether FLOT1 regulates the STING signaling pathway and the transition from an immunogenic tumor to a non-immunogenic tumor in NSCLC." (PMID 37131290, 2023).
cancer (49 papers, 2013 to 2025). A tumor composed of atypical neoplastic, often pleomorphic cells that invade other tissues. "FLOT1 is recognized as a scaffolding protein linked with lipid raft microdomains not only in cancer cells but also presented in neuron projection terminus and distal axon as shown in the cellular component of our GO term enrichment analysis." (PMID 40066501, 2025). "Upregulation of FLOT1 has been associated with poor prognosis in these cancers, indicating its involvement in proliferation and metastasis." (PMID 40335491, 2025). "Another protein, FLOT1, has also been linked to many cancer types and is known to promote tumorigenesis and cancer progression, which leads to poor prognosis." (PMID 39309198, 2024). "Recently, several cancer types are reported to be associated with FLOT1, including breast, renal, oesophageal, colorectal, prostate and lung carcinoma." (PMID 36647700, 2023). "Flotillin-1 (FLOT-1) is a lipid raft-associated protein that has been implicated in the progression of cancers and insulin signaling to trigger glucose transporter redistribution in adipocytes." (PMID 37759431, 2023). "Flotillin-1 and flotillin-2 are frequently overexpressed in cancers and are associated with poor survival." (PMID 29642469, 2018). "During the manuscript preparation, a report was published showing that higher expression of FLOT1 is associated with cancer progression and poor patient survival in ccRCC which is consistent with our results." (PMID 26002553, 2015). "The FLOT1 has been implicated to be a prognostic biomarker in cancer." (PMID 39404386, 2024). "FLOT1, a novel, high confidence gene associated with HannumAge which encodes a marker of lipid rafts, is overexpressed in multiple cancers and negatively associates with cancer prognosis." (PMID 37076473, 2023). "However, the possible role of post-translational modifications of Flot-1 in cadherin-mediated cell–cell adhesion associated with cancer cell invasion and metastasis remains to be demonstrated." (PMID 30631151, 2019). "FLOT1 was originally identified as a marker of lipids, which is important for non-caveolar raft formation and associated with the development and progression of cancer." (PMID 24330780, 2013). "These cancer patients with higher FLOT1 expression had shorter OS time, whereas those with lower FLOT1 expression had longer survival time." (PMID 40066501, 2025). "FLOT1 is a scaffold protein of lipid rafts and has been found to be upregulated in various cancers, making it a potential target for cancer therapy." (PMID 40303305, 2025). "The association between FLOT1 and the IGF1R triggers anti-apoptotic signaling pathways, suggesting their role in activating signaling pathways in human cancers." (PMID 40335491, 2025). "To investigate the role of FLOT1 in radiosensitivity, we applied the FLOT1-related gene signature to the Cancer Cell Line Encyclopedia dataset and stratified cell lines using the BCCP algorithm." (PMID 40335491, 2025). "Next, to further explore the role of FadAL binding to FLOT1 in these processes, the low-expressed FLOT1 cancer cell lines were successfully constructed." (PMID 39193618, 2024). "Given that FLOT1 was overexpressed in several types of cancer, we investigated the expression of FLOT1 in human GBM samples and normal brain tissue by querying TCGA and GTEx databases." (PMID 36647700, 2023). "In contrast, significantly higher signals in flotillin-1 and annexin A1 were detected in m/lEVs derived from cancer cells assessed relative to sEVs." (PMID 36992223, 2023). "Taken together, these data demonstrated that FLOT1 endowed cancer cells with EMT properties, and FLOT1 knockdown inhibited cell migration and alleviated radioresistance in NSCLC cells." (PMID 37131290, 2023).